NAALADL2 (N-acetylated alpha-linked acidic dipeptidase like 2)
Description:
May be catalytically inactive.
Tractability: Antibody: UniProt predicts a signal peptide or a membrane-spanning region.
Gene: Protein-coding gene on chromosome 3 (174,438,573 to 175,810,548, forward strand). Ensembl gene ENSG00000177694.
Subcellular location: Membrane
Subcellular location (Human Protein Atlas): Nucleoplasm
Gene Ontology:
Molecular function: protein binding
Cellular component: nucleoplasm; membrane
Genetic constraint (gnomAD): Loss-of-function variants: 54 observed, 59.58 expected, observed/expected ratio (o/e) 0.91, 90% interval 0.73 to 1.14. The upper end of that interval is the gene's LOEUF score, 1.14, which puts it in group 4 of 6, group 1 being the genes least tolerant of losing a copy. Missense variants: 813 observed, 729.35 expected, observed/expected ratio (o/e) 1.11, 90% interval 1.05 to 1.18. Synonymous variants: 262 observed, 259.57 expected, observed/expected ratio (o/e) 1.01, 90% interval 0.91 to 1.12.
Homologues: Orthologues: chimpanzee NAALADL2 (98% identical), macaque NAALADL2 (95% identical), rabbit NAALADL2 (86% identical), pig NAALADL2 (85% identical), guinea pig NAALADL2 (84% identical), dog NAALADL2 (82% identical), rat Naaladl2 (79% identical), mouse Naaladl2 (78% identical), tropical clawed frog naaladl2 (48% identical). Paralogues in human: NAALAD2 (22% identical), FOLH1 (21% identical), NAALADL1 (21% identical), TFR2 (20% identical), TFRC (18% identical).
Diseases named in the same sentence as NAALADL2 in open-access papers:
NAALADL2 is named in the same sentence as 20 diseases in open-access papers, as found by Europe PMC text mining. Sharing a sentence is not in itself a finding about the gene and the disease. The quoted sentences say what the papers report.
Cornelia de Lange syndrome (3 papers, 2015 to 2019). A rare syndrome characterized by low birth weight, delayed growth, intellectual disabillity, behavioral problems, and a distinctive facial appearance (thin, arched eyebrows, low set ears, small teeth, and small nose). "The NAALADL2 (N-acetylated alpha-linked acidic dipeptidase-like 2) is a giant gene, which is implicated in a rare developmental malformation syndrome, the Cornelia de Lange syndrome." (PMID 26398136, 2015). "NAALADL2 is implicated in the rare developmental malformation Cornelia de Lange syndrome." (PMID 31254375, 2019).
prostate carcinoma (3 papers, 2020 to 2022). A carcinoma that arises from epithelial cells of the prostate gland. "Germline SNPs in the 3q26.31 locus are associated with aggressive prostate cancer, and is the location of NAALADL2, a gene overexpressed in aggressive disease." (PMID 32796921, 2020). "Genome-wide association studies (GWAS) have linked single-nucleotide polymorphisms (SNPs) in NAALADL2 to risk in breast and lung cancers and several studies have identified SNPs within the NAALADL2 locus that are associated with prostate cancer risk or aggression." (PMID 33980983, 2021). "Gains in NAALADL2 were associated with clinical hallmarks of aggressive prostate cancer, including tumour stage, Gleason grade, reduced time to disease recurrence following radical prostatectomy, increased likelihood of a multi-focal tumour, positive surgical margins and lymph node metastasis." (PMID 33980983, 2021). "Copy-number gains in NAALADL2 were found to occur in 15.99% (95% CI:13.02-18.95) of primary prostate cancers with increasing frequency in metastatic, castrate-resistant and neuroendocrine disease." (PMID 33980983, 2021). "A further rs10936845 SNP was identified within a GATA2 motif that increases NAALADL2 expression in prostate cancer patients, where increased expression also predicted biochemical reccurence." (PMID 32796921, 2020). "They find that gains of NAALADL2 and TBL1XR1 in this locus are associated with more aggressive subtypes of prostate cancer and the transcription of pro-proliferative signalling processes." (PMID 32796921, 2020). "The majority of research into the NAALADL2 fragile site has been in prostate cancer." (PMID 33980983, 2021). "In the ICGC cohorts, individuals with somatic single-base alterations in NAALADL2 also associated with reduced disease-free survival in a combined ICGC cohort as well as associating with reduced disease-free and overall survival in an early onset prostate cancer cohort (ICGC EOPC, Denmark)." (PMID 32796921, 2020). "Using publicly-available cancer genomic data we report that NAALADL2 and TBL1XR1 gains/amplifications are more prevalent in aggressive sub-types of prostate cancer when compared to primary cohorts." (PMID 32796921, 2020). "In this study we present evidence that somatic copy-number gains in NAALADL2 and TBL1XR1 are more frequent in high grade and aggressive forms of prostate cancer." (PMID 32796921, 2020).
breast carcinoma (2 papers, 2016 to 2017). "Eight of these 29 (28%) CNV loci were confirmed by qPCR and/or Nanostring analysis, including four loci that were associated with breast cancer (GTF2H2, ZNF385B, NAALADL2 and PSG5) and two loci that were associated with ovarian cancer (CYP2A7 and OR2A1)." (PMID 28145423, 2017). "These include four loci that were associated (unadjusted P<0.05) with breast cancer (GTF2H2, ZNF385B, NAALADL2 and PSG5), and two loci associated with ovarian cancer (CYP2A7 and OR2A1)." (PMID 28145423, 2017).
colon cancer (2 papers, 2016 to 2018). "Microarray studies have shown that NAALADL2 is often overexpressed in prostate and colon cancers and stimulates a migratory and metastatic phenotype." (PMID 29545918, 2018). "In addition, NAALADL2, overexpressed in colon cancer and PCa, has been reported to play significant roles in cancer development and progression." (PMID 27409348, 2016).
Kawasaki disease (2 papers, 2015 to 2017). A rare inflammatory disease characterized by an acute febrile, systemic, self-limiting, medium-vessel vasculitis primarily affecting children. "Since Kawasaki disease affects blood vessels and BD is also a form of vasculitis, the fact that NAALADL2 showed a novel association with intestinal BD in both our replication and subsequent haplotype analyses is intriguing." (PMID 28045058, 2017). "In addition, one GWA study of Kawasaki disease, a pediatric vasculitis that damages coronary arteries, reported a marker (rs17531088, p = 1.13 x 10−6) in the NAALADL2 gene associated with Kawasaki disease." (PMID 26398136, 2015).
Age-related cataract (1 paper, 2021). A type of cataract (opacification of the lens) that forms during the course of aging. "We found that variants in the genes associated with age-related cataracts, including NAALADL2 and ACSL1, functioned in the metabolism pathway." (PMID 34299682, 2021). "Some of these genes associated with age-related cataracts include FRMD4B, NAALADL2, LOC105377670, LINC00968, LOC101929415, CTNNA3, LOC107984170, PRCP, and ZNF423, whereas others with a reduced risk include CFAP74, ACSL1, LOC101927668, LOC105369844." (PMID 34299682, 2021).
autism spectrum disorder (1 paper, 2018). A spectrum of developmental disorders that includes autism, and Asperger syndrome. "The NAALADL2 gene has been implicated to cause autism spectrum disorder, a neurodevelopmental disorder." (PMID 30034349, 2018).
colorectal cancer (1 paper, 2017). A primary or metastatic malignant neoplasm that affects the colon or rectum. "Immunohistochemical analyses for NAALADL2 and YIPF7 were performed using inflamed colon tissues obtained from patients with intestinal BD or IBD and normal colon tissues obtained from patients with colorectal cancer after intestinal surgery." (PMID 28045058, 2017).
endometriosis (1 paper, 2017). The growth of functional endometrial tissue in anatomic sites outside the uterine body. "Of these eight loci, three were associated with all endometriosis (LAMC3, CAPN14 and DEFA1), and six with Stage B disease (NAALADL2, NR2C1, C14orf132, FOXP2, CDH20 and LAMC3)." (PMID 28333195, 2017).
epidermolysis bullosa (1 paper, 2021). Epidermolysis bullosa (EB) is a group of genetic skin diseases that cause the skin to blister very easily. "The partial deletion of LAMA3 is responsible for epidermolysis bullosa in horses; NAALADL2 is believed to be responsible for immune homeostasis, and TAFA2 (FAM19A2) is believed to be responsible for the regulation of feed intake and metabolic activities in mice." (PMID 34051743, 2021).
prostate tumors (1 paper, 2016). "Of these, EFHD1, MLPH, NAALADL2 and KLK15 are significantly upregulated while others are downregulated in prostate tumors compared to normal samples." (PMID 27409348, 2016).
cancer (9 papers, 2016 to 2024). A tumor composed of atypical neoplastic, often pleomorphic cells that invade other tissues. "Knockdown of Naaladl2 has shown decreased cell viability accompanied by increased apoptosis in previously published cancer studies." (PMID 37872881, 2023). "One example is NAALADL2, one of the most frequently altered fragile sites in the cancer genome." (PMID 33980983, 2021). "This suggests that gains in these genes may cause increased expression of NAALADL2 and TBL1XR1 in cancers." (PMID 32796921, 2020). "This study centred around two genes; NAALADL2 and TBL1XR1, both of which are attractive therapeutic targets with TBL1XR1 previously suggested as a potential cancer target; operating via the TGF-β signalling pathway and potentially regulating AR signalling." (PMID 32796921, 2020). "In addition, NAALADL2 also regulate the expression of master regulator (Ser133 phosphorylated C-AMP-binding protein) of cellular processes involved in the development and progression of cancer." (PMID 27884161, 2016).
tumour (7 papers, 2016 to 2025). "NAALADL2 is a member of the NAALADase protein family which act as matrix metalloproteases and have the ability to alter the tumour environment." (PMID 29545918, 2018). "N-acetyl-l-aspartyl-l-glutamate peptidase-like 2 (NAALADL2) belongs to glutamate carboxypeptidase II family, NAALADL2 has been reported to localize to the basal cell surface and affect the adhesion, migration and invasion of tumor cells." (PMID 27884161, 2016). "The closest gene to NAALADL2 is TBL1XR1, which is implicated in tumour development and progression." (PMID 32796921, 2020). "However, data exist implicating NAALADL2 in tumour development and progression." (PMID 33980983, 2021). "A proposed mechanism is that since NAALADL2 has been found to be basal-localized, it may enhance interaction of tumour cells with the extracellular matrix surrounding the tumour and provide a mechanism for the tumour cells to escape." (PMID 29545918, 2018). "In primary disease, gains/amplifications occurred in 15.99% (95% CI: 13.02–18.95) and 14.96% (95% CI: 12.08–17.84%) for NAALADL2 and TBL1XR1 respectively, increasing in frequency in higher Gleason grade and stage tumours." (PMID 32796921, 2020). "AC022893.2 and NAALADL2.AS2 have not found evidence related to tumor prognosis in the currently published studies." (PMID 33777735, 2021).
NAALADL2 also shares sentences with these, for which no sentence is quoted: vasculitis (2 papers); asthma (1); Crohn disease (1); lung carcinoma (1); neurodevelopmental disorder (1); ovarian carcinoma (1); viral infections (1).